TXNDC16 (thioredoxin domain containing 16)
Synonyms: ERP90; KIAA1344
Tractability: Antibody: UniProt places it where antibodies can reach, with high confidence; UniProt predicts a signal peptide or a membrane-spanning region; its Gene Ontology location is reachable by antibodies, with medium confidence. PROTAC: ubiquitination databases record sites on it; its protein half-life has been measured.
Gene: Protein-coding gene on chromosome 14 (52,429,472 to 52,553,563, reverse strand). Ensembl gene ENSG00000087301.
Subcellular location: Secreted; Endoplasmic reticulum lumen
Subcellular location (Human Protein Atlas): Mitochondria; Predicted to be secreted
Gene Ontology:
Molecular function: protein binding
Cellular component: endoplasmic reticulum lumen; extracellular exosome; extracellular region
Genetic constraint (gnomAD): Loss-of-function variants: 50 observed, 50.74 expected, observed/expected ratio (o/e) 0.99, 90% interval 0.78 to 1.25. The upper end of that interval is the gene's LOEUF score, 1.25, which puts it in group 5 of 6, group 1 being the genes least tolerant of losing a copy. Missense variants: 745 observed, 745.29 expected, observed/expected ratio (o/e) 1, 90% interval 0.94 to 1.06. Synonymous variants: 264 observed, 261.75 expected, observed/expected ratio (o/e) 1.01, 90% interval 0.91 to 1.12.
Homologues: Orthologues: chimpanzee TXNDC16 (99% identical), macaque TXNDC16 (95% identical), dog TXNDC16 (87% identical), pig TXNDC16 (83% identical), guinea pig TXNDC16 (82% identical), rabbit TXNDC16 (76% identical), mouse Txndc16 (76% identical), rat Txndc16 (72% identical), tropical clawed frog txndc16 (45% identical), zebrafish txndc16 (36% identical).
Diseases named in the same sentence as TXNDC16 in open-access papers:
TXNDC16 is named in the same sentence as 5 diseases in open-access papers, as found by Europe PMC text mining. Sharing a sentence is not in itself a finding about the gene and the disease. The quoted sentences say what the papers report.
asthma (1 paper, 2012). "Similarly to the SNPs in AHNAK, a SNP in the TXNDC16 gene also influenced asthma risk in interaction with rhinitis." (PMID 22432035, 2012). "We compared the gene expression levels of genes found to be relevant in asthma in the SNP analysis in sputum samples of 12 asthmatics and 9 controls using TaqMan Gene Expression Assays (FRMD6, PTGDR, PTGER2, MS4A2, AHNAK, PRPF19, TXNDC16)." (PMID 22432035, 2012).
breast carcinoma (1 paper, 2025). "For TGFB2-dependent biomarkers, elevated TGFB2 mRNA expression is a prognostic biomarker associated with breast cancer patients that is correlated with improved OS outcomes at high expression levels of GDAP1, TBL1XR1, RNFT1, HACL1, SLC27A2, NLE1, and TXNDC16." (PMID 41373732, 2025). "In cases dependent on TGFB2, increased mRNA expression of TGFB2 alongside higher levels of GDAP1, TBL1XR1, RNFT1, HACL1, SLC27A2, NLE1, or TXNDC16 was correlated with improved OS among breast cancer patients, of which four genes were upregulated in tumor tissues (SLC27A2, TXNDC16, TBL1XR1, GDAP1)." (PMID 41373732, 2025).
meningioma (1 paper, 2024). A generally slow growing tumor attached to the dura mater. "Thioredoxin domain containing 16 (TXNDC16) is a known meningioma-associated antigen." (PMID 38673779, 2024).
tumor (2 papers, 2022 to 2025). "Four of these genes were significantly upregulated in tumor tissues (p < 0.0001 for all comparisons): SLC27A2, TXNDC16, TBL1XR1, and GDAP1." (PMID 41373732, 2025).
TXNDC16 also shares sentences with these, for which no sentence is quoted: rhinitis (1 paper).